GNAS (GNAS complex locus)
Diseases named in the same sentence as GNAS in open-access papers (continued):
Sharing a sentence is not in itself a finding about the gene and the disease.
progressive osseous heteroplasia (27 papers, 2011 to 2025). A rare genetic bone disorder characterized clinically by progressive extraskeletal bone formation presenting in early life with cutaneous ossification, that progressively involves subcutaneous and then subsequently deep connective tissues, including muscle and fascia. "Osteoma cutis is associated with normal serum levels of calcium and phosphorus throughout life, which suggests that the mutation is on the paternal GNAS allele." (PMID 29959430, 2018). "Hedgehog (Hh) signaling plays a crucial role in intramembranous ossification diseases, particularly in progressive osseous heteroplasia (POH), which is caused by heterozygous null mutations in the GNAS." (PMID 39364140, 2024). "Rare genetic disorders caused by heterozygous inactivating mutations of the GNAS locus, including progressive osseous heteroplasia (POH), are associated with HO that forms within the skin." (PMID 33574833, 2021). "Human genetic diseases, such as progressive osseous heteroplasia (POH), are caused by inactivating mutations in GNAS encoding the α-subunit of the stimulatory G protein (Gsα) that abrogate the activation of adenylate cyclase." (PMID 32629962, 2020). "Other related genetic disorders include Albright hereditary osteodystrophy (AHO) and progressive osseous heteroplasia (POH), both of which result from inactivating mutations in the guanine nucleotide-binding protein, alpha stimulating activity polypeptide (GNAS)." (PMID 40806642, 2025). "Progressive osseous heteroplasia (POH) is another ultra-rare genetic disease caused by heterozygous inactivating mutations in GNAS exons 1–13 and is characterized by cutaneous ossifications that proceed into the subcutaneous and deep connective tissues, including muscles, tendons, and ligaments." (PMID 35296306, 2022). "Furthermore, progressive osseous heteroplasia (POH) is a distinct entity described in patients with paternally inherited GNAS mutations, usually causing truncation of the gene product." (PMID 29280743, 2017). "Furthermore, GNAS gene mutations were described also in patients with Progressive Osseous Heteroplasia (POH) and primary Osteoma Cutis (OC) broadening the spectrum of Gsα-related disorders and representing two important differential diagnosis." (PMID 27871293, 2016). "Progressive osseous heteroplasia (POH; OMIM number: 166350) is known to show progressive ankylosis and growth retardation caused by ectopic ossification due to mutations in GNAS, which encodes Gαs." (PMID 32933018, 2020). "This is of relevance due to the fact that a mutation in GNAS has been shown to activate hedgehog signaling, which has been shown to cause cutaneous ossification in conditions such as progressive osseous heteroplasia (POH), osteoma cutis Albright hereditary osteodystrophy (AHO)." (PMID 28421001, 2017). "Disorders of GNAS inactivation include various phenotypes, including PHP Ia, Ib, and Ic; pseudoPHP (PPHP); progressive osseous heteroplasia (POH), and osteoma cutis (OC)." (PMID 34740356, 2021). "In some patients with GNAS mutations, SCO can appear without other features of AHO and is therefore termed osteoma cutis, but may later evolve into AHO with or without its associated hormonal abnormalities." (PMID 21747923, 2011). "Interestingly, an entity termed progressive osseous heteroplasia (POH), which occurs predominantly secondary to paternal inheritance of GNAS mutations with absence of other AHO features, may well represent an extreme variant of AHO involving heterotopic bone formation." (PMID 21747923, 2011). "They found that most individuals with superficial or progressive ossification had mutations in GNAS, but there were no specific genotype-phenotype correlations that distinguished the more progressive forms of HO (eg, POH) from the nonprogressive forms (osteoma cutis, AHO, and PHP1a/c)." (PMID 21559111, 2011).
colorectal cancer (26 papers, 2012 to 2025). A primary or metastatic malignant neoplasm that affects the colon or rectum. "Gains were observed in chromosomes 13q12‐13 and 20q13.32, which have been associated with early events in the development of colorectal cancer, also affecting GNAS." (PMID 39876058, 2025). "GNAS mutations have been reported in up to 3% of colorectal carcinomas, most exhibiting a villous morphology." (PMID 39309469, 2024). "Only two studies on colorectal cancer patients in our study reported other GNAS codons: R201S and Q227H mutations, respectively." (PMID 36428574, 2022). "GNAS gene mutation early identification is important as a prognosticating biomarker for colorectal cancer screening and diagnosis." (PMID 36428574, 2022). "Through this study, the authors aim to determine the global prevalence of GNAS gene mutation in patient diagnosed with colorectal cancer." (PMID 36428574, 2022). "Data from published full exome sequences of colorectal cancer have suggested that GNAS mutations are quite often accompanied by mutations in KRAS and/or BRAF." (PMID 35141142, 2021). "GNAS mutations were rare in a parallel cohort of 121 advanced colorectal cancers (2.5 %), but were associated with peculiar clinical-pathological features and aggressive course." (PMID 27154293, 2016). "The purpose of this study is to determine the genetic frequency of GNAS activating mutations in colorectal cancer and the corresponding pathology of GNAS mutant tumors." (PMID 24498230, 2014). "GNAS was shown to be activated through amplification primarily in ovarian cancer as well as through activating mutations in colorectal cancer." (PMID 22879877, 2012). "Notably, UrCAs tend to exhibit a lower frequency of TERT and RB1 alterations than BAC, whereas SMAD4 and GNAS mutations, which are frequently observed in colorectal cancer, are more commonly identified in UrCA." (PMID 39857670, 2025). "Just as with the KRAS, the GNAS gene mutations are frequently detected in lots of tumour types, detected in about 5% of all sequenced malignant tumours, as well as 4–7% in colorectal cancers (CRCs), 41% in intraductal papillary neoplasms of the pancreas and about 15% in liver cancer." (PMID 36428574, 2022). "GNAS genes are mutated at a significant frequency in colorectal cancer (CRC)." (PMID 36428574, 2022). "Reports on overexpression of the GNAS gene in cancers and, linked with tumourigenesis metastasis and progression are vast; however, the detailed understanding of the genetic contribution of GNAS mutation in colorectal cancer (CRC) progression remains ambiguous and unclear." (PMID 36428574, 2022). "However, evidence on the pathogenetic and prognostic role of GNAS mutations in colorectal cancer cannot be considered definitive given their rarity and the retrospective nature of our data." (PMID 27154293, 2016). "However, our retrospective large cohort of patients seemed to identify GNAS-mutated colorectal cancer as associated with aggressive clinical course and phenotypic characteristics resembling to PMP (right side origin, mucinous histology, peritoneal involvement and concomitant KRAS mutations)." (PMID 27154293, 2016). "GPR176 facilitates colorectal cancer progression through its interaction with GNAS, leading to the inhibition of mitophagy." (PMID 40316942, 2025).
colorectal cancer (continued). "GPR176 has been found to activate the cAMP/PKA pathway in colorectal cancer, and its transmembrane helix 3-intracellular loop 2 domain has been observed to recruit GNAS, thereby amplifying the intracellular GPR176 signal." (PMID 37584712, 2023). "GPR176 promotes colorectal carcinoma progression by interacting with the G protein GNAS." (PMID 40689396, 2025). "Nishikawa and colleagues previously demonstrated cAMP-mediated elevation of MUC2 and MUC5AC expression in stably transfected HT29 colorectal cancer cell line expressing GNAS, thereby supporting the role for GNAS expression and cAMP/PKA signaling pathway in the regulation of mucin production." (PMID 29290997, 2017). "Interestingly, the introduction of the mutant GNAS into a colorectal cancer cell line markedly induced MUC2 and MUC5AC expression, but did not promote cell growth either in vitro or in vivo." (PMID 24312577, 2013). "Further possible events that favoured transformation are the gain of the oncogenes GNAS (a PDAC driver gene), LINC00659 (an oncogene in colorectal cancer), and ZNF217 (an oncogene in many solid tumours, including PDAC)." (PMID 36289850, 2022). "The role of GNAS R201C and R201H in CRC tumourigenesis under the control of the Gpa33-antigen promoter is almost exclusively expressed in colorectal cancer." (PMID 36428574, 2022). "The role of GNAS gene codons R201C and R201H in CRC tumourigenesis under the control of the Gpa33-antigen promoter is almost exclusively expressed in colorectal cancer." (PMID 36428574, 2022). "Moreover, full exome sequencing of colorectal cancer samples by our group and collaborators revealed coincident GNAS and KRAS mutations in a small cohort of colon tumors, indicating GNAS mutations in colon cancers might also often be accompanied by mutations in KRAS and/or BRAF." (PMID 24498230, 2014). "The aberrations found in this study (losses of TSC2, COL1A1, NOTCH1, MIR4673 and GNAS, and gains of MALAT1 and TALAM1) may serve as candidate biomarkers for early detection of colorectal cancer onset." (PMID 35887000, 2022).
pseudohypoparathyroidism type 1B (25 papers, 2007 to 2026). Pseudohypoparathyroidism type 1B (PHP-1b) is a type of pseudohypoparathyroidism (PHP) characterized by localized resistance to parathyroid hormone (PTH) mainly in the renal tissues which manifests with hypocalcemia, hyperphosphatemia and elevated PTH levels. "We identified two novel, small, recurrent variants in the GNAS gene in patients with autosomal dominant and sporadic pseudohypoparathyroidism type 1B that are associated with broad defects in methylation of the GNAS locus." (PMID 39541438, 2024). "Abnormal GNAS imprinting causes pseudohypoparathyroidism type 1B (PHP1B), a prototype of mammalian end-organ hormone resistance." (PMID 36853809, 2023). "Pseudohypoparathyroidism type 1b (PHP-1b) is a rare genetic disorder caused by mutations or epigenetic alterations of the maternal GNAS gene, resulting in isolated renal resistance to parathyroid hormone (PTH) and, in some cases, partial resistance to thyroid-stimulating hormone." (PMID 41884215, 2026). "Pseudohypoparathyroidism type 1B (PHP1B), caused by abnormal methylation of the GNAS gene leading to parathyroid hormone (PTH) resistance, lacks Albright hereditary osteodystrophy features and is often misdiagnosed." (PMID 40893942, 2025). "Pseudohypoparathyroidism type 1b (PHP 1b) is an imprinting disorder involving the GNAS region of the 20 chromosome." (PMID 30871545, 2019). "Pseudohypoparathyroidism type 1B (PHP1B; MIM#603233) is a rare imprinting disorder (ID), associated with the GNAS locus, characterized by parathyroid hormone (PTH) resistance in the absence of other endocrine or physical abnormalities." (PMID 29445425, 2018). "Interestingly, a distinct methylation pattern at the GNAS locus in Patient #1 aligns with pseudohypoparathyroidism Type 1B, confirmed by additional analyses, suggesting overlapping genetic conditions complicating the clinical and DNA methylation profiles." (PMID 39603792, 2025). "Furthermore, epigenetic GNAS changes, as in pseudohypoparathyroidism type Ib (PHP1B), can lead to excessive weight." (PMID 32318528, 2020). "Furthermore, variable methylation levels ranging from an apparently normal level to a severely skewed level at different DMRs of a single imprinted region have been described only for GNAS-DMRs in patients with sporadic pseudohypoparathyroidism type Ib." (PMID 30846001, 2019). "Second, the ExAC data set does not allow an evaluation of epigenetic changes that may contribute to specific disease phenotypes (e.g., alterations in methylation at the GNAS locus in pseudohypoparathyroidism Ib)." (PMID 29308445, 2017). "A2 methylation of GNAS is regulated by STX16 and NESP55 imprinting control regions, and GNAS A2 methylation status enables pseudohypoparathyroidism type 1B categorization." (PMID 38290008, 2024). "Pseudohypoparathyroidism type 1B (PHP1B) results from aberrant genomic imprinting at the GNAS gene." (PMID 38290008, 2024). "In addition, global methylation analysis also revealed hypomethylation at the GNAS A/B:TSS-DMR locus, suggestive of pseudohypoparathyroidism, type 1B (PHP1B) (OMIM: 603233)." (PMID 38751117, 2024). "Another case of severe pseudohypoparathyroidism type 1b was reported in a child with a broad epigenetic defect without deletion in the GNAS region." (PMID 30349702, 2018).
acromegaly (21 papers, 2015 to 2026). Acromegaly is an acquired disorder related to excessive production of growth hormone (GH) and characterized by progressive somatic disfigurement (mainly involving the face and extremities) and systemic manifestations. "The aggregate prevalence of somatic GNAS mutations in acromegaly was 38% in the systematic review, which was similar to the prevalence of 41% at our institution." (PMID 41648725, 2026). "GNAS mutations are prevalent among Chinese acromegaly patients, correlating with reduced pituitary tumor sizes and enhanced GH secretion functions." (PMID 39513543, 2025). "This study aims to address these gaps by examining GNAS mutations and delineating the detailed clinical profile of affected patients within a Chinese acromegaly cohort." (PMID 39513543, 2025). "What is more, we inventively identified gender disparities in the clinical characteristics associated with GNAS mutations, emphasizing the need to give importance to gender factors in future clinical and foundational research on acromegaly." (PMID 39513543, 2025). "In the present study, we found that 44.3% (43/97) of sporadic acromegaly patients carried somatic GNAS mutations in a large Chinese cohort." (PMID 39513543, 2025). "Our research provides an in-depth analysis of how somatic GNAS mutations influence the clinical features of patients with acromegaly." (PMID 39513543, 2025). "In summary, we suggested that somatic GNAS mutations were important genetic factors in Chinese acromegaly patients." (PMID 39513543, 2025). "GNAS mutations (GNAS-MT) have been proposed to trigger different acromegaly clinical characteristics through the altered expression of components in these important pathways." (PMID 36435867, 2022). "Transcriptomic group 3 includes predominantly sparsely granulated somatotroph PitNETs with low GNAS mutations frequency causing ~35% of acromegaly." (PMID 36497102, 2022). "The results suggested that GNAS mutations impact endocrinological features in acromegaly through GPCR pathway induction." (PMID 36435867, 2022). "It has also been shown that GNAS mutations have an impact on clinical features of acromegaly, to further study how these mutations affect functionality of pituispheres extended investigation should be performed." (PMID 32528411, 2020). "A recent case report described a patient with a heterozygous guanine nucleotide-binding protein G(s) subunit alpha (GNAS) R201C mutation in a somatotroph adenoma." (PMID 33574795, 2020). "Somatic mutations in GNAS can result in sporadic somatotroph adenomas, while mosaic mutations for codon 201 likely result in McCune–Albright syndrome." (PMID 33574795, 2020). "GNAS-mutated tumors are often smaller and less invasive, respond better to SSAs, and are usually densely granulated somatotroph adenomas." (PMID 33574795, 2020). "Some studies have demonstrated that GNAS loss of methylation at maternal promoter is associated to response to somatostatin analogs and contributes to the pathogenesis of acromegaly." (PMID 29947650, 2018). "Addison’s is often autoimmune, while acromegaly typically lacks autoimmunity, but shared mechanisms, such as genetic predispositions (e.g., HLA or GNAS mutations) or HPA axis dysregulation, could link these disorders." (PMID 40842744, 2025). "Somatic GNAS mutations are acknowledged as a significant etiological factor for acromegaly." (PMID 39513543, 2025). "Therefore, our study is designed to explore the GNAS mutation status and gender-specific characteristics based on a large Chinese acromegaly cohort." (PMID 39513543, 2025). "Sparsely granulated somatotropinomas typically occur in young acromegaly individuals and may be associated with genetic mutations, such as somatic GNAS or germline AIP mutations." (PMID 37958702, 2023).